BRCA1 (BRCA1 DNA repair associated)
Diseases named in the same sentence as BRCA1 in open-access papers (continued):
Sharing a sentence is not in itself a finding about the gene and the disease.
breast cancer (continued). "Kristiansen and colleagues investigated the XCI in breast cancer, revealing a higher frequency of skewed XCI in women aged 27 to 45 years compared to matched controls, while the likelihood of carrying the BRCA1 or BRCA2 mutation is unrelated to the XCI pattern." (PMID 35456502, 2022). "In fact, in our specific case (the BRCA1 gene and breast cancer), the LOH of the wild-type allele is not systematic, but the probability is sufficient to propose the likelihood of neutrality or pathogenicity." (PMID 35039532, 2022). "Breast cancer gene-1 (BRCA1) and breast cancer gene-2 (BRCA2) are players in the HRR machinery." (PMID 36230726, 2022). "Breast cancer susceptibility gene (BRCA) mutations, including BRCA1, are found in several tumors." (PMID 36118697, 2022). "This retrospective study demonstrated that the reversion mutations were observed in three HRR-associated genes (BRCA1, BRCA2 and PALB2) with four cancer types (breast cancer, pancreatic cancer, ovarian cancer, and lung cancer) from this Chinese pan-cancer patient cohort." (PMID 35281878, 2022). "In addition, BRCA1/BRCA2 MINAS women were significantly more likely than BRCA1 or BRCA2 women to have had breast cancer." (PMID 34983940, 2022). "Germline BRCA1/2 mutations are associated with increased susceptibility to EOC and breast cancer, with a lifetime risk of developing EOC estimated at 40–60% for BRCA1 and 11–27% for BRCA2 mutation carriers, compared with 1.3% of women in the general population." (PMID 35735457, 2022). "In this study, we aimed to identify shared (or common or public) neoantigens found recurrently in BRCA1-related breast cancer patients that may be used as target neoantigens for shared vaccine development." (PMID 36298462, 2022). "Overall, 54.9% of the cohort had BRCA1/2 testing within 6 months of breast cancer diagnosis." (PMID 35312162, 2022). "At present, most BRCA1/2 mutation carriers with breast cancer do not receive PARPi prior to their first recurrence." (PMID 36344544, 2022). "Some studies have found that the overexpression of UBE2T may promote the occurrence of breast cancer during the whole process of BRCA1 downregulation." (PMID 36088429, 2022). "They identified 12.4% of breast cancers as being BRCA1/2-deficient although they did not present a BRCA1/2 germline mutation." (PMID 36077638, 2022). "We found that among early stage, HR-positive, HER2-negative breast cancer patients, BRCA1/2 PV carriers receive more intensive, platinum-based chemotherapy regimens than other patients, for which there is neither evidence of benefit nor guideline recommendation." (PMID 35723570, 2022). "On this basis, we next considered if VNGD could be exploited as combinatorial target for synthetic lethal approaches, and in particular, whether targeting VNGD could confer PARPi sensitivity in breast cancer cells expressing WT BRCA1." (PMID 36047643, 2022). "Our study identified common somatic mutations that are predicted to be immunogenic in BRCA1-related breast cancer (BRCA1-positive, -negative, and germline BRCA1 mutations)." (PMID 36298462, 2022). "The study noted that TGFBR1*6A allelic frequency among Caucasians from the UK does not differ by age of onset (<40 years), bilateral breast cancer, family history, and germline mutations of BRCA1 and BRCA236." (PMID 35853889, 2022). "MyCode participants with a P/LP BRCA1/2 variant were significantly more likely than participants without a BRCA1/2 variant to have a history of breast cancer (odds ratio, 5.95) or ovarian cancer (odds ratio, 18.3)." (PMID 35692820, 2022). "Additionally, ALKBH5 decreases breast cancer sensitivity to doxorubicin by removing the m6A methylation of BRCA1 for mRNA stabilization and increases DNA repair competency." (PMID 36551544, 2022).
breast cancer (continued). "This study also shows that the risk having both ovarian cancer and breast cancer is higher in BRCA1 than in non-BRCA group (trend)." (PMID 35469032, 2022). "Women with a BRCA1 mutation are at risk for a range of cancers other than breast cancer, but it has not been established that thyroid cancer is part of the BRCA1 cancer spectrum." (PMID 35205705, 2022). "S100A8 and S100A9 specifically have been shown to have altered expression levels in breast cancer tissues compared with normal tissues, with increased expression levels associated with non-functional BRCA1 (BReast CAncer gene 1)." (PMID 35471994, 2022). "However, other contributing factors for this association need to be investigated such as defects in homologous recombination (e.g., BRCA1, BRCA2, PALB2, ATM, CHEK2) known to increase risk of breast cancer." (PMID 36421330, 2022). "Surprisingly, 19% of BRCA1/2 carriers conceive within 10 years after breast cancer diagnosis." (PMID 35062994, 2022). "However, survey study regarding expertise of specialists involved in breast care showed some gaps of knowledge regarding fertility and pregnancy management in BRCA1/2- related breast cancer survivors." (PMID 35062994, 2022). "Among women with human epidermal growth factor receptor 2 (HER2)-negative breast cancer, those with germline BRCA1/2 mutations tend to be diagnosed at a younger age and more frequently have a family history of the disease." (PMID 35907135, 2022). "Moreover, in families with BRCA mutations, there is an increased risk of male breast cancer, although the risk appears to be greater with inherited BRCA2 mutations than with inherited BRCA1 mutations." (PMID 35885460, 2022). "Germline BRCA1 and BRCA2 loss-of-function variants predispose to development of breast cancer." (PMID 36324133, 2022). "We developed a Bayesian network model of a hypothetical cohort of carriers of BRCA1 or BRCA2 diagnosed with stage I/II unilateral breast cancer and treated with breast-conserving treatment who underwent subsequent second primary cancer risk–reducing strategies." (PMID 36580360, 2022). "PVs in BRCA1 and BRCA2 possess a 50% to 80% lifetime risk of developing breast cancer." (PMID 35323371, 2022). "In the present study, we show that when HspBP1 is either knocked down or overexpressed in BRCA1-proficient breast cancer cells, there were profound changes in tumorigenesis, including anchorage-independent cell growth in vitro and in tumor formation in xenograft models." (PMID 35387978, 2022). "BRCA1/2 carriers can consider surgical prophylactic strategies such as bilateral salpingo-oophorectomy and mastectomy, as well as enhanced breast cancer screening; strategies demonstrated to reduce the risk of cancer related death in these high-risk individuals." (PMID 35735457, 2022). "Breast cancer 1 (BRCA1) and breast cancer 2 (BRCA2) tumour‐suppressor genes have been identified as two significant susceptibility genes in breast cancer, with mutations in the BRCA1 and BRCA2 genes involved at least 30% of hereditary breast cancer cases." (PMID 35762299, 2022). "The risk is also relatively higher than in men with first-degree relatives and those with breast cancer gene mutation 2 (BRCA2) rather than breast cancer gene mutation 1 (BRCA1)." (PMID 36686127, 2022). "As we previously showed that PR is not methylated in the absence of progesterone, we proposed that PRMT1 could be a novel actor of PR downregulation prior to hormonal stimulation, acting with BRCA1 in the recycling of unliganded PRs in breast cancer cells." (PMID 36076907, 2022). "However, pathogenic mutations in BRCA1 and BRCA2 increase the risk of breast cancer by 65% and 45%, respectively." (PMID 35743744, 2022). "Many breast cancer patients who had a higher inherited risk of developing the disease tested negative for BRCA1 or BRCA2 P/LP-Vs, necessitating additional genetic testing using larger gene panels." (PMID 36140642, 2022).
breast cancer (continued). "Ten patients carried high risk BRCA1 mutant genes, and 17 women had a history of family or personal breast cancer, and they all presented with benign or negative mammograms." (PMID 35953551, 2022). "While inactivating BRCA1 germline mutations are linked to a small portion of the total number of breast tumor cases worldwide, the cloning and subsequent characterization of the BRCA1 gene had an unprecedented impact on our understanding of breast cancer etiology." (PMID 35432218, 2022). "Furthermore, HER2-negative breast cancers were significantly more prevalent among BRCA1 (98.2% vs 77.7%, p < 0.001) and BRCA2 (95.0% vs 77.7%, p = 0.001) PV carriers than non-PV carriers." (PMID 35135604, 2022). "However, this estimate is most likely biased because male breast cancer family history has been an important factor in considering BRCA1/2 germline genetic testing since the discovery of BRCA1/2." (PMID 35077220, 2022). "While previous candidate gene studies of common genetic variants linked PPARGC1A with ovarian cancer and familial breast cancer risk, our WGS study, focusing on rare and functional variants, was the first to reveal the effect of PPARGC1A in the context of BRCA1/2 mutation." (PMID 35625955, 2022). "Second, the DALYs for individuals with a disease are assumed to be the same among those with and without the genetic exposures (for example, individuals with and without a damaging BRCA1 mutation that develop breast cancer accumulate DALYs similarly)." (PMID 36097220, 2022). "Compared to breast cancer and ovarian cancer, BRCA1/2 mutations alone do not pose a significant risk of pancreatic cancer." (PMID 35163129, 2022). "The study was conducted in the German population in breast cancer patients without BRCA1/BRCA2 mutations." (PMID 35456414, 2022). "Genetic mutations such as mutation of BRCA1 and BRCA2 genes also contribute to breast cancer." (PMID 35454076, 2022). "DrABC generates probabilities of whether a breast cancer patient carries GPVs in BRCA1/2, other CPGs except for BRCA1/2, or any CPG." (PMID 35209950, 2022). "Our study provides lists of potential shared neoantigens among BRCA1-related breast cancer, which may be used in developing off-the-shelf neoantigen-based vaccines." (PMID 36298462, 2022). "BRCA1 also surfaced in the breast cancer-specific analysis (pLOF, p = 6.68 × 10−8)." (PMID 36199081, 2022). "Additionally, BRCA1 normally functions to control the migration of breast cancer cells, which limits metastasis within the body." (PMID 35740092, 2022). "Assessing the HRs for CNV versus non-CNV pathogenic variants, separately for BRCA1 and BRCA2 suggested elevated breast cancer risk for BRCA1 deletions (HR = 1.21, 95%CI = 1.09–1.35) but not BRCA2 deletions." (PMID 36203093, 2022). "The potential risk of IVF treatment in the setting of germline mutations, such as breast cancer gene (BRCA1 and BRCA2), was not analysed, however the evidence suggests that IVF is safe in patients with such mutations." (PMID 35143625, 2022). "However, our sample was enriched by breast cancer patients; therefore, a high prevalence of P/LPVs in BRCA1/2 was expected." (PMID 36132150, 2022). "Deregulated expression of BRCA1 as a result of aberrant IGF signaling might bear consequences in breast cancer development." (PMID 35432218, 2022). "Mutations in the BRCA1 and BRCA2 genes are known risk factors and drivers of breast cancer." (PMID 36276952, 2022).
breast cancer (continued). "These variables were also associated with BRCA1 PVs carrier status except grade, whereas BRCA2 was only associated with younger age, HER2-negativity, higher grade and first degree family history of breast cancer." (PMID 35143328, 2022). "In both cases, broadlyaccepted breast cancer drivers such as BRCA1 and ESR1 are central nodes in the network.The network analysis has revealed severalinfluential DCDs that are not curated CGC genes yet, for example E2F2 and THRA fromsingle-cell, and SIN3A from bulk data." (PMID 36124841, 2022). "Furthermore, BRCA1 mutations in breast cells can autonomously activate RANKL expression and trigger breast cancer susceptibility." (PMID 36199692, 2022). "In contrast, most sporadic breast cancers are ER+ because their BRCA1 genes are usually intact." (PMID 34996912, 2022). "However, it should be noted that in this region the extensive genetic testing of BRCA1/2 genes has been carried out in patients with ovarian and breast cancer, as well as, in healthy patients since the year 2000." (PMID 35382848, 2022). "According to two large-scale clinical researches based on Chinese breast cancer patients published in 2017, the authors reported negative results because BRCA1 mutation was not significantly correlated with poor prognosis in multivariate analysis." (PMID 34403063, 2022). "Thus, we tested the efficacy of combination treatment with a chemical inhibitor of S100A9 or CXCL12 and αPD1 in BRCA1-MT mice, and found the treatment significantly inhibited mammary tumor growth, recurrence, and metastasis." (PMID 35304461, 2022). "However, BC onset can be also caused by inherited or acquired mutations in specific genes, such as BRCA1 and BRCA2 (breast cancer gene 1 and 2)." (PMID 36358854, 2022). "In addition, PARP14 depletion suppressed olaparib and cisplatin-induced apoptosis in RPE1-BRCA1KO cells, as well as the cisplatin sensitivity of MDA-MB-436 patient-derived BRCA1-mutant breast cancer cells." (PMID 36030235, 2022). "Two ovarian and breast cancer patients with BRCA1/2 LGR benefited from PARPi therapy." (PMID 36147908, 2022). "Breast cancers caused by deficiency of breast cancer-associated gene 1 (BRCA1) do not have an improved response to the treatment." (PMID 35304461, 2022). "Expression of BRCA1/2 in breast cancer tissues is significantly higher than in normal tissue." (PMID 35409110, 2022). "Further therapeutic targeting of RAD51 in BRCA1 L1780P mutant breast cancer is warranted." (PMID 35626017, 2022). "Of the five patients with BRCA1 mutations, four had TNBC and one had HR+ breast cancer." (PMID 35907135, 2022). "Germline defects in BRCA1/2 can be found in approximately 10% of breast cancers." (PMID 35907135, 2022). "In our study triple-negativity is seen in 38% of BRCA1 breast cancers." (PMID 35469032, 2022). "Moreover, BRCA1 and BRCA2 mutation is seen in 80-90% of single gene familial breast cancers and about 3-6% of all breast cancers." (PMID 36705103, 2022). "The prognostic role of BRCA mutations in ovarian and breast cancer is well established; BRCA2 mutated breast cancer displays worse prognosis compared to sporadic cancer, while, in BRCA1, no substantial differences were observed." (PMID 35200549, 2022). "Moreover, ATAD2 is a critical intermediary of DNA damage response and repair in breast cancer cells, through mediating Chk1, Chk2, and BRCA1, which have an essential role in the dissolution of DNA damage foci and homologous recombination in BC." (PMID 36008934, 2022).
breast cancer (continued). "In addition, NUSAP1, similar to BRCA1, plays a role in DNA double-stand break repair via the homologous recombination and single-strand annealing pathways in breast cancer, and it protects BRCA1 from proteasome-mediated degradation." (PMID 35739489, 2022). "Interestingly, we noted that the impact of RRBSO in patients with the BRCA1 and BRCA2 pathogenic variants with luminal breast cancer in stage I/II increased with the age." (PMID 36580360, 2022). "Survival time for breast cancer patients did not have a significant association with ER status (p = 0.16), age at diagnosis (p = 0.47), BRCA1 vs. BRCA2 germline mutation (p = 0.4), tumor stage at diagnosis (p > 0.74), or patient recurrence status (p = 0.58)." (PMID 36344544, 2022). "But the elevated risk for PC was also noted in patients with breast cancer with a negative test for BRCA1 and BRCA2 mutations." (PMID 35761384, 2022). "Additionally, one patient was diagnosed with an early‐stage breast cancer based on follow‐up for a BRCA1 PGV identified through genetic testing in the MDPC." (PMID 35906821, 2022). "Several clinical trials such as the OlampiAD study for breast cancer, SOLO study for ovarian cancer, and TOPARP-B study for prostate cancers with underlying germline BRCA1/2 mutations have shown promising results with an increase in response rate and progression-free survival (PFS)." (PMID 35228986, 2022). "Along this line, CtIP germline variants have been recently identified in Danish cohorts of breast cancer patients negative for pathogenic mutations of BRCA1 and BRCA2." (PMID 35203293, 2022). "Using different risk models for pathogenic BRCA1 and BRCA2, we observed that the predicted risk was higher in breast cancer cases carrying germline loss-of-function variants in BRCA1 and/or BRCA2 than in other breast cancer genes, or those carrying wild-type genes." (PMID 35353237, 2022). "BRCA1 or BRCA2 mutations are associated with high penetrance rates; the estimated mean cumulative risks for breast cancer by age 70 years for BRCA1 and BRCA2 mutation carriers, as reported by a meta-analysis, were 57% (95% CI, 47% to 66%) and 49% (95% CI, 40% to 57%), respectively." (PMID 35402282, 2022). "The authors also noted that the BRCA1/2 mutation carriers were younger at breast cancer diagnosis than non-carriers (mean age 45.5 vs 50.3 years, P < 0.0001)." (PMID 34467476, 2022). "Our study fills an important evidence gap and adds support to the lack of increased cardiotoxicity risk in breast cancer patients with BRCA1/2 mutations." (PMID 35242827, 2022). "The underlying mechanism of increased cytotoxicity by combined EZH2/ATM inhibition in BRCA1-deficient breast cancer cells is not clear." (PMID 35715861, 2022). "Even though our BRCAness score was generated based on BRCA1 mutation tumors, this relationship was not always the case in breast cancer cell lines." (PMID 36371386, 2022). "However, there has been limited study and therefore poor understanding of the role of BRCA1 in sporadic breast cancer." (PMID 36942145, 2022). "To investigate the contribution of host STING to the anti-tumor efficacy of PARPi plus a STING agonist in Brca1-deficient breast tumors, we employed STING−/− mice (Tmem173gt/gt, C57BL/6J) and EO771 murine breast cancer cells, a syngeneic mouse model on C57BL/6 background." (PMID 35641483, 2022). "In parallel with our study, one group has investigated the prevalence of BRCA gene mutation in Saudi women with breast cancer; they found that mutation of BRCA2 gene was found in 7 patients out of 310 with total percentage of both BRCA1 and BRCA2 of 12.9%; the percentage of BRCA2 was 2.2%." (PMID 36268271, 2022). "To assess whether this could be recapitulated by human BRCA1-mutant breast cancer cells, we treated THP-1 macrophages with CM collected from BRCA1-mutant breast cancer cell lines MDA-MB-436 or HCC1937." (PMID 35641483, 2022). "BRCA1 and BRCA2 are the most mutated genes in breast cancer." (PMID 36362151, 2022).